WDR88 (WD repeat domain 88)
Synonyms: PQWD
Tractability: PROTAC: ubiquitination databases record sites on it.
Gene: Protein-coding gene on chromosome 19 (33,132,090 to 33,175,799, forward strand). Ensembl gene ENSG00000166359.
Subcellular location (Human Protein Atlas): Golgi apparatus; Nucleoplasm
Genetic constraint (gnomAD): Loss-of-function variants: 40 observed, 47 expected, observed/expected ratio (o/e) 0.85, 90% interval 0.66 to 1.11. The upper end of that interval is the gene's LOEUF score, 1.11, which puts it in group 4 of 6, group 1 being the genes least tolerant of losing a copy. Missense variants: 562 observed, 626.73 expected, observed/expected ratio (o/e) 0.9, 90% interval 0.84 to 0.96. Synonymous variants: 235 observed, 251.24 expected, observed/expected ratio (o/e) 0.94, 90% interval 0.84 to 1.04.
Homologues: Orthologues: chimpanzee WDR88 (99% identical), pig WDR88 (70% identical), dog WDR88 (69% identical), rabbit WDR88 (64% identical), rat Wdr88 (62% identical), mouse Wdr88 (60% identical), tropical clawed frog wdr88 (39% identical). Paralogues in human: DAW1 (21% identical), WDR62 (20% identical), TEP1 (17% identical), MAPKBP1 (17% identical), WDR7 (14% identical), PAFAH1B1 (14% identical), WDR17 (13% identical), WDR27 (13% identical), AHI1 (12% identical), NEDD1 (12% identical), WDR5B (12% identical), WDR81 (12% identical), and 14 more.
Diseases named in the same sentence as WDR88 in open-access papers:
WDR88 is named in the same sentence as 8 diseases in open-access papers, as found by Europe PMC text mining. Sharing a sentence is not in itself a finding about the gene and the disease. The quoted sentences say what the papers report.
schizophrenia (3 papers, 2016 to 2022). A major psychotic disorder characterized by abnormalities in the perception or expression of reality. "First, the association evidence for WDR88 (p = 0.003) which we previously reported to be associated with schizophrenia, was considerably diminished by addition of the Swedish data, suggesting the previous report is likely to be a false positive." (PMID 28719003, 2017). "WDR88 has previously been associated with schizophrenia; however, the function of the gene remains unclear." (PMID 36167494, 2022).
candidiasis (1 paper, 2022). Infection with the organism Candida. "In the cross-tissue analysis, only the association between increased risk of candidiasis and the genetically predicted increased expression of WDR88 was significant (p-value = 1.83 × 10–6)." (PMID 36167494, 2022). "The T allele of rs10422015 in WD repeat-containing protein 88 (WDR88) was associated with the increased risk of candidiasis (OR, 1.31; 95% [1.19–1.44]; p = 3.11 × 10–8)." (PMID 36167494, 2022). "The replication of this LRP3/candidiasis and WDR88/candidiasis association in various tissues suggests that there may be mechanisms common across tissues." (PMID 36167494, 2022). "In TWAS, four gene-disease associations were significant: SLC30A9 for otitis media (p = 8.06 × 10–7); LRP3 and WDR88 for candidiasis (p = 3.91 × 10–7 and p = 1.95 × 10–6); and AAMDC for hepatitis B (p = 1.51 × 10–6)." (PMID 36167494, 2022). "An additional new observation was an association between the WDR88/LRP3 region and the risk of candidiasis; further, TWAS also showed that the genetically determined expression of WDR88 and LRP3 in a variety of tissues associated with altered risk of candidiasis." (PMID 36167494, 2022).
prostate carcinoma (1 paper, 2021). A carcinoma that arises from epithelial cells of the prostate gland. "WD repeat domain 88 (WDR88) present on chromosome 19 is known to be important biomarker for early prostate cancer development." (PMID 34441816, 2021).
uterine carcinoma (1 paper, 2023). A carcinoma involving a uterus. "In uterine carcinoma cells, one Supertarget was the WDR88 gene encoding a protein with six WD40 repeat domains; however, information about its functions is lacking." (PMID 37297004, 2023).
WDR88 also shares sentences with these, for which no sentence is quoted: hepatitis B (1 paper); leukemia (1); lung disease (1); otitis media (1).